EPHA2 (EPH receptor A2)
Diseases named in the same sentence as EPHA2 in open-access papers (continued):
Sharing a sentence is not in itself a finding about the gene and the disease.
cancer (continued). "Moreover, STAT3 (-1.83), EphA2 (-1.74) and BMP7 (-47.17), all proteins involved in signalling pathways associated with cancer stem cell activities, were also found to be down-regulated in the proteomics datasets." (PMID 29568355, 2018). "Other studies that demonstrate upregulation of ephrin-A3 in NSCLC and inhibitory effects of ephrin-A3 and ephrin-B2 on transactivation of EphA2/EphA3 and EphA3/EphB4, respectively, are indicative of context-dependent aberrations of Eph/ephrin molecules in cancer cells." (PMID 29682554, 2018). "Furthermore, EphA2 is overexpressed in multiple cancer types (breast, brain, ovary, bladder, prostate, pancreas, esophagus, lung, and stomach)." (PMID 30222105, 2018). "EphA2 is a promising target for therapeutics of different cancer types." (PMID 30222105, 2018). "It has been acknowledged that the EphA2-mediated angiogenesis process in cancer occurs via the recruitment of phosphoinositide 3-kinase (PI3K) and the stimulation of downstream molecules of the Vav family of guanine nucleotide exchange factors (GEFs) and Rac1-GTP." (PMID 30914876, 2018). "This interaction is expected to mainly induce pro-oncogenic effects in cells therefore, inhibition of the Ship2-Sam/EphA2-Sam complex may represent an innovative route to discover anti-cancer therapeutics." (PMID 29234063, 2017). "This suggests that, in addition to the expression of MT1-MMP and EphA2, other factors could be involved in releasing the EphA2 fragment into blood vessels from cancer cells." (PMID 29072678, 2017). "SETD2, PTEN, RNF43, HRAS, EPHA2, and BAP1 were also linked to primarily positive associations in more than one cancer type, suggesting that they may play a general role in CGI hypermethylation." (PMID 29125844, 2017). "Therefore, processing of EphA2 by MT1-MMP in cancer cells represents an important cancer progression-related event." (PMID 29072678, 2017). "Having described the signalling and trafficking events linking RCP to EphA2 function in cell:cell repulsion we wished to determine whether these two proteins contributed to cancer-relevant processes in an appropriate in vivo context." (PMID 28294115, 2017). "If the cleaved N-terminal domain of EphA2 is released from cells and circulates stably in patient blood, it could be a useful biomarker for early detection in cancer patients using a conventional blood test." (PMID 29072678, 2017). "Besides the adjuvant function, TPE-Py-FFGYSA can selectively light up EphA2 protein clusters overexpressed in cancer cells in a fluorescence turn-on mode, by taking advantage of the specific YSA peptide (YSAYPDSVPMMS)–EphA2 protein interaction." (PMID 28507673, 2017). "The recent discovery of progranulin as a novel EphA2 ligand provides support for the notion that disparate proteins may recognize EphA2 as a cognate receptor within a cancer context." (PMID 29290990, 2017). "Therefore, a ligand-initiated cell morphology assessment was performed in a panel of EphA2-expressing cancer cell lines to assess the potential functional involvement of eHsp90." (PMID 29290990, 2017). "It is likely that various EphA2 forms from non-cancerous cells diminish the sensitivity and specificity of that assay as a diagnostic tool for cancer patients." (PMID 29072678, 2017). "EphA2 expression then reappeared in cancer specimens, along with increased positivity for TF." (PMID 27246245, 2016). "This leads to a pathological imbalance between the EphA2 receptor and ephrin ligands that may be important for promoting the ligand-independent oncogenic potential of EphA2 in various cancer cell types." (PMID 27619642, 2016). "In addition, oncogenic EphA2 signaling has been proposed to be ligand-independent, drawing from the observations of decreased expression of the ephrin-A1 ligand paralleling increased EphA2 expression in human cancers." (PMID 27246245, 2016).
cancer (continued). "Since we report the Anks1a ANK domain interacts with the TKD of EphA2, it may represent a novel therapeutic target for the treatment of cancer." (PMID 27619642, 2016). "Among fellow RTKs, EPHA1, EPHA2, FGFR2, PDGFRß, Ret, and VEGFR2 have often been linked to cancer." (PMID 26073592, 2015). "In accordance with our results, previous studies demonstrated that inhibition of EphA2 overexpression by siRNA knockdown or blocking antibody could lead to decreased malignant cellular behavior or progression in a variety of cancer cells." (PMID 26177500, 2015). "There is evidence that EphA2 modulates the sensitivity of cancer cells to chemotherapeutic agents." (PMID 25351620, 2015). "EPHA2 is reported to be oncogenic in several cancers and is also known to promote metastasis." (PMID 25366905, 2015). "Considering these observations together with our results, KRAS-mediated activation of the ERK–RSK pathway regulates not only EphA2 protein expression but also the phosphorylation of EphA2, which consequently results in high level expression of pS-EphA2 leading to cancer metastasis." (PMID 26158630, 2015). "In summary, we have demonstrated the previously unknown connection of RSK to EphA2, and this pathway is involved in the malignant progression of cancer cells, such as migration and invasion." (PMID 26158630, 2015). "EphA2 is a receptor tyrosine kinase often overexpressed in many human cancers." (PMID 25788424, 2015). "Recent studies have demonstrated that RhoA could act as an important signaling molecule that mediates EphA2 activation, promoting malignant cellular behavior in several types of cancer." (PMID 26177500, 2015). "As EphA2 can be highly expressed in a broad range of cancer types, the prognostic utility of this marker may prove significant in the monitoring and clinical management of a large cohort of cancer patients." (PMID 25013485, 2014). "In terms of this point, Miao and his colleagues reported on the diametrically opposite roles of EphA2 in regulating cell migration and invasion; while activation of EphA2 with ephrin-A1 inhibited migration of cancer cells, EphA2 overexpression promoted migration in a ligand-independent manner." (PMID 24606764, 2014). "EphA2 is persistently overexpressed and functionally changed in numerous human cancers." (PMID 24959216, 2014). "Overexpression of EphA2 had been observed in many human cancers." (PMID 24864260, 2014). "Moreover, E-cadherin can promote EphA2 expression and surface localization in epithelial and cancer cells, thereby prolonging EphA2 interaction with ephrin-A1." (PMID 24606764, 2014). "EphrinA1 expression has been significantly associated with EphA2 expression, although ephrinA1 was not an independent prognostic factor in several types of cancer." (PMID 23738943, 2013). "EphA2 overexpression in several types of cancers has been correlated with poor patient outcome." (PMID 22370972, 2013). "Expressions of EphA2, EphA4, and ephrinA1 were mainly observed in the cytoplasm of cancer cells." (PMID 23738943, 2013). "EphA2 has been found to be upregulated during the angiogenic process of several cancers." (PMID 24705208, 2013). "We have detected inhibitory cis interactions with ephrins in cancer cells not only for EphA3, which had been previously studied in neurons, but also for endogenous EphA2 and EphB4, for which the effects of cis interactions have not been previously investigated." (PMID 24348920, 2013). "Tyrosine kinases such as EphA2 or EMP1 could be very interesting targets in cancer therapy because these cell surface molecules are more appropriate therapeutic targets than transcription factors." (PMID 24287901, 2013). "Thus, in cancer cells cis interaction with endogenous ephrin-A ligands can attenuate EphA2 activation by ephrin-As presented in trans, supporting the significance of cis interactions in cancer pathogenesis." (PMID 24348920, 2013).
cancer (continued). "Future optimization of the structure of doxazosin through chemical derivatization may lead to the discovery of new EphA2 agonists with enhanced affinity, specificity, and potency for use as more effective cancer therapeutics." (PMID 22916121, 2012). "Similar to its ligand, the role of EphA2 in cancer is somewhat conflicting." (PMID 22853000, 2012). "This ability to transform fibroblasts and some epithelial cell types, as well as its high expression levels in several different types of cancer, suggests that EPHA2 may have a direct role in oncogenesis." (PMID 20979646, 2010). "Thus, due to its expression pattern, localization, and functional importance in treatment outcome, EphA2 is an attractive target for therapeutic agents in ovarian as well as other cancers." (PMID 20064265, 2010). "Thus, the interaction of EphA2 with members of the EGFR family indicates a functional role for EphA2 in EGFR-expressing cancer cells." (PMID 20064265, 2010). "EphA2 is also frequently overexpressed and functionally altered in many invasive cancers." (PMID 18797457, 2008). "Although it remains unclear if the activation of EphA2 tyrosine kinase is necessary for its role in cancer progression, our results suggest that more selective small molecule inhibitors of EphA2 might also have clinical value." (PMID 18797457, 2008). "Furthermore, we identified several RNA-binding proteins, including HuR, that interact with these clusters, and we show that EfnA2, EphA2, and EphA4 are direct posttranscriptional targets of HuR in cancer cell lines." (PMID 18648668, 2008). "However, EphA2 is frequently overexpressed or activated in human cancers." (PMID 41280086, 2025). "•Src, but not AKT, drives EphA2 upregulation in PTEN-deficient cancers." (PMID 41130297, 2025). "EphA2-targeted nanoparticles are, in most cases, liposomes, i.e., spherical vesicles with a lipid bilayer that can be loaded with small interfering RNAs (siRNAs) or drugs for targeted delivery to cancer cells, or polymeric nanoparticles made from biodegradable polymers." (PMID 39596256, 2024). "Additionally, the EphA2 expression may be useful for monitoring cancer during postoperative surveillance if it is effective in distinguishing between healthy individuals and patients with cancer." (PMID 39766211, 2024). "EphA2, a cancer-promoting factor in OSCC, might be involved in regulating CSC properties." (PMID 38916835, 2024). "This phosphorylation is able to localize EphA2 at the frontier of migrating cells, leading to actin cytoskeleton framework assembly and lamellipid membrane formation, promoting and maintaining certain cancer cell functions, such as cell motility and proliferation." (PMID 37980165, 2023). "Inhibition of EphA2 in normal tissues while fighting cancer may lead to unintended toxic effects." (PMID 37063424, 2023). "In addition to these roles, EphA2 is a key regulator of tumorigenesis and cancer progression." (PMID 36142306, 2022). "It was found that the proteolytic cleavage of EphA2 by MT1-MMP initiated increased cleaved EphA2 translocation to the intracellular compartment and increased activity of RhoA small GTPase, which, in turn, caused a repulsive effect between cells, and promoted single cancer cell invasion." (PMID 36132127, 2022). "In addition, our previous studies also identified the stimulatory effect of C1GALT1-mediated O-glycosylation on RTK activity such as EPHA2, integrin, and MET in several adult cancers and C1GALT1 high expression was associated with poor survival of patients in these studies." (PMID 35169131, 2022).
cancer (continued). "Because the results from cancer cell lines indicated that expression levels of EPHA2 influenced infection—a two-fold to five-fold increase of expression resulted in double the numbers of infected cells—we compared the expression levels in cancer cell lines and organoids." (PMID 33596248, 2021). "The effects of this phosphorylation include localisation of EphA2 at the leading edge of migrating cells, allowing for actin cytoskeleton assembly and the formation of lamellipodia, thereby leading to the promotion and maintenance of certain cancer cell features such as motility and proliferation." (PMID 33430066, 2021). "However, the mechanisms by which the EphA2-associated super-enhancer and its cofactors regulate its target genes are not clear, and their biological functions in cancer cells remain unexplored." (PMID 33712565, 2021). "However, comparing cancer organoid lines from three patients, expression levels of EPHA2 did not fully mirror infectivity, and one cancer organoid line with very low expression level of EPHA2 was also infectable." (PMID 33596248, 2021). "Other miRs have been linked to cancer stemness depending of the expression of certain tyrosine kinase receptors, such as EphB2 and EphA2, whose expression marks early and late CRC, respectively, EphB2 being a marker of staminality and EphA2 being expressed in the invasive CRC phase." (PMID 34065438, 2021). "In addition, AKT can reverse-regulate p-EPHA2 to promote malignant proliferation of cancer cells." (PMID 33834064, 2021). "Inhibition of EphA2 by AWL‐II‐41‐27, EphA2‐specific tyrosine kinase inhibitor, or knock‐down of EphA2 decreased mRNA and protein expression of cyclin‐dependent kinase (CDK) 6 in CC cells, which increased cellular susceptibility to epirubicin (EPI), an anti‐cancer chemotherapy drug." (PMID 33586348, 2021). "Indeed, the inhibition of EphA2 sensitizes cancer cells to anticancer therapies." (PMID 32756339, 2020). "In addition, EphA2 possesses ligand-independent kinase activity in cultured cancer cells, which might partially explain its malignant effects in the non-phosphorylated state." (PMID 32811512, 2020). "Although EPHA2 plays a critical role in cancers, how EPHA2 activity is regulated remains unclear." (PMID 32005975, 2020). "But whether HDAC7 regulates EphA2 expression in cancer is unclear." (PMID 32376822, 2020). "The EphA2/ephrin A1 system could be targeted for cancer treatment at least via two mechanisms." (PMID 32811512, 2020). "Moreover, membrane-anchored membrane type-1 matrix metalloproteinase (MT1-MMP) has been found to cleave EphA2 and trigger intracellular EphA2 translocation, leading to increased RhoA activity, cell junction disassembly, and single cancer cell invasion via cell repulsion." (PMID 28194092, 2017). "Therefore, EphA2 has been suggested as a novel target for cancer treatment." (PMID 28624791, 2017). "Therefore, specific detection of the cleaved N-terminal EphA2 fragment in blood might be an effective biomarker to diagnose malignant tumors." (PMID 29072678, 2017). "Moreover, whether KRAS status or mutations of other cancer driver genes in CRC patients (TCGA database) might have led to lack of CEACAM5 interaction with the other studied genes (CEACAM1, CEACAM6 and EPHA2) will need further investigation." (PMID 29262644, 2017). "This implies that the products of EphA2 cleavage could constitute markers for cancer progression." (PMID 29072678, 2017). "Since the ER must supply the mature forms of EphA2 and ErbB2 required for the synergistic and oncogenic signalling of these receptors at the cell surface, the precise mechanism by which these receptors are effectively exported from the ER in cancer cells is an important unresolved question." (PMID 27619642, 2016). "Moreover, EPHA2 can function as a therapeutic target for antibody therapy of cancers and diseases." (PMID 27681698, 2016).
cancer (continued). "Consequently, our new finding on the functional connection between RSK and EphA2 encourages further study to characterize fully the cooperation of these two kinases with integrins and Rho GTPases in the motility of cancer cells, cell–cell adhesion and cell–ECM interaction." (PMID 26158630, 2015). "In contrast, the regulation of EphA2 overexpression is still largely unknown; therefore, further detailed study is needed to understand fully the molecular mechanisms behind the high expression of pS-EphA2 in cancer cells." (PMID 26158630, 2015). "In addition, given the widespread expression of EphA2 in epithelial carcinoma, novel therapeutic compounds conjugated with the EphA2 receptor may be an effective way to target paclitaxel to cancer cells." (PMID 25351620, 2015). "These lines express high levels of ephrin-A ligands together with EphA2 (broadinstitute.org/ccle), although the receptor is expressed at relatively low levels, consistent with the complementary expression of Eph receptors and ephrins observed in many cancer cell lines." (PMID 24348920, 2013). "Furthermore,EphA2 or EphB4 inhibition could reduce ameboid-type migration of cancer cells andcould stabilize epithelial adherens junctions in various cancer cell lines, assuggested by Fang and Yang." (PMID 21479221, 2011). "Among them, EphA2 and ephrinA1 are the most widely studied with respect to development, tumorigenesis, angiogenesis, and metastasis and they may represent as the potential therapeutic targets because of their diverse functions in several types of cancer." (PMID 21264258, 2011). "Therefore, Hsp90 inhibition may represent a therapeutic approach to neutralize receptor function and reduce the aggressiveness of EphA2-driven cancers." (PMID 20628489, 2010). "However, little is known about what factors determine whether EPHA2 augments or suppresses cancer progression." (PMID 20979646, 2010). "Indeed, stimulation of certain EPHA2 overexpressing cancer cell lines with recombinant EFNA1-Fc fusion proteins has been shown to suppress oncogenesis by causing receptor internalization and in normal epithelial cells EFNA1 functions at cell-adhesions to stabilize E-cadherin adhesion complexes." (PMID 20979646, 2010). "Overall, EphA2-79 and EphA2-85 CAR-T cells efficiently recognized and killed EphA2 in target cancer cells in vitro." (PMID 40181964, 2025). "Our computational study suggested that a few cancer-related SASH1-Sam1 variants, with mutations inside the ML interface (i.e., L667P and Y659C), could more likely disturb the Sam1 domain fold and consequently avoid interaction between EphA2-Sam and SASH1-Sam1 through a kind of indirect mechanism." (PMID 39942820, 2025). "Cancer cells were NucLight Red-labeled and co-cultured with either α-CD19-CAR-Ms or α-EphA2-CAR-Ms, compared to untransduced (UTD) macrophages." (PMID 40595560, 2025). "In Ras/MAPK mutant cancers, a conserved gene signature that includes ETV4/5, SPRY2/4, DUSP4/6, and EPHA2/4 is a reliable biomarker of pathway activation and is associated with good clinical response to MEK inhibitor therapy." (PMID 41446112, 2025). "Next, we evaluated the effect of MBZ on the ubiquitination and expression levels of EphA2, and observed that MBZ significantly increased EphA2 ubiquitination levels, and decreased EphA2 expression levels in the NPC cancer cells." (PMID 39897046, 2025). "Although EphA2, the primary receptor of Ephrin A1, has been reported to induce EMT of cancer cells, the function of Ephrin A1 in cancer EMT was unconfirmed." (PMID 39838173, 2025). "Although the relationship between EphA2 and YAP is supported by our and others’ results, knowledge of the connection between YAP and KLF4 is limited in cancer." (PMID 38916835, 2024). "This approach capitalizes on the specificity of YSA-LP for EphA2-expressing cells to facilitate targeted delivery of DOX, thereby improving the therapeutic impact on cancer cells through increased precision and potency." (PMID 38612592, 2024).